AR (androgen receptor)
Diseases named in the same sentence as AR in open-access papers (continued):
Sharing a sentence is not in itself a finding about the gene and the disease.
prostate carcinoma (continued). "In three AR-positive prostate cancer cell lines, PRPF6 was lowly expressed in LNCaP cells that expressed AR-FL but not AR-Vs." (PMID 33390843, 2021). "With so many known alternative pathways available to a prostate cancer cell seeking to bypass drug treatments, the time-limited responses to ADT based on AR signaling inhibitors is perhaps not surprising." (PMID 33477370, 2021). "Later on, a direct interaction between the HH-GLI and AR signaling pathways was found, suggesting a completely new, non-canonical function for the HH-GLI signaling pathway in prostate cancer." (PMID 34290270, 2021). "We recently reported that dietary WBM antagonized DHT-induced AR activation and PSA expression in prostate cancer animal models and mouse prostate glands, without observable body weight loss, hepatotoxicity, and nephrotoxicity." (PMID 34341347, 2021). "Though there have been no reports regarding prostate cancer, the effect of a feedback pathway has been observed involving ATP citrate lyase, AMP kinase, and AR attenuates tumor growth and the acquiring of cisplatin resistance in ovarian cancer." (PMID 34822423, 2021). "A negative feedback loop, encompassing AR-driven downregulation of miR-204, inhibition or XRN-1, and downregulation of miR-34a, which enables re-expression of AR, was described in prostate cancer cells." (PMID 34940756, 2021). "DHT does not induce the secretion of the prostate cancer serum marker, Prostate Specific Antigen (PSA) and AR protein in S‐EVs." (PMID 34434533, 2021). "From a mechanistic viewpoint, abiraterone acetate and enzalutamide, which target the AR signaling pathways, are the only FDA-approved drugs for prostate cancers, but these drugs are not effective against AR-null prostate cancers." (PMID 33572730, 2021). "In breast and prostate cancer, the most aggressive and difficult to treat tumors are ER negative (ie, TNBC) and androgen receptor (AR) null (ie, neuroendocrine prostate cancer)." (PMID 33094211, 2020). "In prostate cancer, DAXX has been demonstrated to act as a negative androgen receptor (AR) partner and inhibits AR-mediated promoter activity through direct protein-protein interactions." (PMID 31942198, 2020). "Altogether these results suggest AR reprogramming, rather than inactivation, as a general survival strategy in ARI-resistant prostate cancer cells." (PMID 32427840, 2020). "Despite this possible regulation of miR-4287 by AR, we observed a similar downregulation of EMT pathway mediators and stem cell marker CD44 in both AR negative (PC3) and AR positive (LNCaP) cell line emphasizing its tumor-suppressor role in prostate cancer." (PMID 33473254, 2020). "While PARP1 levels are not regulated by AR, PARG inhibition has a potential to synergize with castration therapy and be more effective in reducing cancer burden in men with advanced prostate cancer." (PMID 32123273, 2020). "Ectopic expression of ESRP1 and ESRP2 protein expression in AR negative PC3 and DU145 cell line models reduced prostate cancer cell growth in vitro." (PMID 31478829, 2019). "Using a panel of prostate cancer cell lines, we demonstrated that MYC suppression—rather than AR suppression—is a key determinant of BET bromodomain inhibitor sensitivity." (PMID 30846826, 2019). "Genome-wide analysis on the target genes of AR indicated a direct negative regulation of COUP-TFα by AR, in which COUP-TFα localized in the nucleus in prostate cancer epithelium but not in nonmalignant prostate epithelium." (PMID 31212954, 2019). "Although there appeared to be some interaction between AR and PI3K signaling in the ovarian cancer cell lines, it was not reciprocal as it is in prostate cancer." (PMID 34926721, 2019). "On the other hand, the survival of AR-negative PC3 and Du145 prostate cancer, MiaPaca2 pancreatic carcinoma, HeLa cervical cancer, or WI38 human fibroblast cells was only slightly affected." (PMID 31431473, 2019).
prostate carcinoma (continued). "To model advanced prostate cancer, we used the human prostate cancer cell lines DU145 and PC3, both of which are negative for androgen receptor signaling." (PMID 31653272, 2019). "One interesting observation is a reciprocal negative feedback regulation between AR and PI3K/Akt signaling pathways in prostate cancer." (PMID 31552182, 2019). "A reciprocal relationship between the AR and PI3K pathway in ovarian cancer is not yet confirmed as it is in prostate cancer." (PMID 34926721, 2019). "In this context, a recent study provided evidence that the histone demethylase JMJD1A promotes alternative splicing of AR-7 in prostate cancer cells: interestingly, knockdown of JMJD1A inhibited splicing of AR-V7, but not AR-WT, in a minigene reporter assay." (PMID 31366128, 2019). "Expression of mutant SPOP activates PI3K/AKT pathway and upregulates AR signaling, maintaining AR transcriptional activity against PI3K/AKT‐mediated negative feedback, effectively activating the two most common driver pathways critical in prostate cancer." (PMID 29572264, 2018). "All human prostate cancer cells showed a time-dependent increase in DHT production and the highest DHT production at 48 h regardless of cell type (i.e., androgen receptor-positive or negative)." (PMID 29164416, 2018). "To determine if our observations were restricted to AR-negative PC3 cells, we set up direct co-cultures of the myofibroblasts with the AR-positive LNCaP and C4-2B, and the AR-negative DU145, prostate cancer cell lines." (PMID 29721186, 2018). "Four different prostate cancer cell lines (22Rv1 and LNCaP cells, which are androgen receptor-positive cells; DU145 and PC-3 cells, which are androgen receptor-negative cells) were used to determine the best cell line for the screening system." (PMID 29164416, 2018). "Particularly in prostate cancer, one of the major hurdles is the existence of negative feedback between AKT and AR signaling pathways, making a single blockage of AKT signaling inefficient in the treatment of prostate cancer." (PMID 29523594, 2018). "The presence or absence of AR expression in the PShTert-AR and PShTert myofibroblasts and the PC3, LNCaP, C4-2B, and DU145 prostate cancer cells used in this study was confirmed by western immunoblot." (PMID 29721186, 2018). "Unlike some other prostate cancer cell lines (i.e., PC3 cells), the CWR22Rv1 cells express a constitutively active androgen receptor and PSA, characteristics shared by castrate-resistant prostate cancer in humans." (PMID 29914450, 2018). "Next, we compared levels of the miRNAs (521, 885 and 324) among non-neoplastic prostate epithelial (RWPE1) and various prostate cancer cell lines – LNCaP (AR+), PC-3 (AR–) and DU145 (AR–) – and exosomes secreted by these cells." (PMID 29568403, 2018). "The effects were observed not just with AR-negative PC3 cells, but also with AR-positive LNCaP and C4-2B, and AR-negative DU145 prostate cancer cell lines." (PMID 29721186, 2018). "Although prostate cancer CHP-1 cells, which were obtained from a castrated dog, do not express the AR, the cells with AR exhibited androgen-dependent AR signalling." (PMID 28599655, 2017). "To reinforce the idea that SEMA3C expression requires AR, we also showed that SEMA3C levels were not induced by R1881 in the AR-negative prostate cancer cells lines, PC-3 and DU 145, over the same concentrations." (PMID 28038451, 2017). "Since PC3 cells express neither full-length AR nor AR target PSA, this enabled us to determine the effects of RSV on the ectopically expressed ARV7 in a prostate cancer cellular environment but without the effects of the endogenously expressed ARs." (PMID 28903374, 2017). "Evidence supporting the in vivo efficacy of targeting the AR NTD was shown by application of decoy AR1-558 molecules of AR NTD that inhibit the growth and hormonal progression of prostate cancer xenografts both in the presence and absence of androgen." (PMID 28306720, 2017).
prostate carcinoma (continued). "While, a novel prostate cancer and lineage-specific LncRNA PCAT14, which is transcriptionally regulated by AR, is overexpressed in low grade disease and lack of PCAT14 predicts for disease aggressiveness and recurrence in PCa." (PMID 28915709, 2017). "Initially we noticed that ∼ one fifths of our prostate cancer samples were cribriform tumors; we then analyzed the expression patterns of NRIP, AR, and DDB2 in the context of the prostate cancers with or without the cribriform pattern." (PMID 28212551, 2017). "Unlike prostate cancer cell lines, very few PDAC cells express relatively lower levels of AR protein, whereas others lack any detectable AR expression." (PMID 28881737, 2017). "Our results support a regulatory axis whereby CXCR7 is upregulated in the absence of AR signaling, which drives alternative EGF-mediated cell survival signaling, leading to androgen-independent prostate cancer progression." (PMID 28596572, 2017). "Here, we isolated plasma membranes from the prostate cancer cell line DU145, not expressing the classical intracellular AR." (PMID 28290516, 2017). "Indeed, radium-223 has been demonstrated to extend survival in prostate cancer patients with bone metastases showing a non-overlapping mechanism of action and different toxicity profile than pre-existing therapies such as androgen receptor (AR) inhibitors, immunotherapy, and chemotherapy." (PMID 29283383, 2017). "In a castration-resistant prostate cancer model, EZH2 acted as a co-activator for critical transcription factors including the androgen receptor (AR) that was independent of its transcriptional repressor function." (PMID 28410242, 2017). "Human prostate cancer PC-3 cells, which are AR negative and ETS-1 positive, were co-transfected with EBS-Luc, AR vector, or empty vector." (PMID 29312607, 2017). "RT-PCR analysis revealed the expression of all three types of AR transcripts in three AR-positive breast and prostate cancer cell lines (MDA-MB-453, VCaP, and LNCaP) and normal breast and prostate tissues but not in the AR-negative liver cancer Huh7 cell line." (PMID 28035996, 2016). "Inhibition of mTORC1 by salinomycin in AR-negative PC3 and DU145 prostate cancer cells was reported." (PMID 27557496, 2016). "Nevertheless, since the tumor suppression effects were observed by increasing and decreasing NKAIN2 expression level in the AR negative PC3 cells, NKAIN2 can clearly suppress prostate cancer cell growth and migration in cells without androgen activity." (PMID 27588475, 2016). "The kinetics of γH2AX formation and resolution in AR-negative HMC18 cells was unaffected by ENZ treatment, while DHT hastened γH2AX resolution in AR-positive C4–2 prostate cancer cells." (PMID 27109210, 2016). "Of particular relevance to prostate cancer, the androgen receptor has been found to regulate a suite of DDR genes, including some that promote resistance to radiotherapy in prostate cancer in part by promotion of non-homologous end joining (NHEJ) repair." (PMID 26485759, 2015). "To further validate these observations, we co-immunoprecipitated β-catenin with AR and FKBP52 from LNCaP prostate cancer cell lysates in the presence or absence of a transiently transfected siRNA targeting FKBP52." (PMID 26207810, 2015). "Even though the role of USP10 in prostate cancer has not been investigated, it is interesting to note that USP10 is also involved in the regulation of the androgen receptor." (PMID 25605410, 2015). "Inhibition of the PI3K pathway alone causes growth arrest but not significant tumor regression in Pten-negative prostate cancers, however, combined PI3K and AR pathway inhibition gives profound tumor regressions." (PMID 26506516, 2015). "We found higher expression levels of Cx43 in androgen receptor negative prostate cancer cell lines PC-3 and DU145 compared with their androgen receptor positive counterparts LNCaP and C4-2." (PMID 25960544, 2015).
prostate carcinoma (continued). "In AR-negative cell lines, RUNX1 knockdown enhances, while RUNX1 overexpression inhibits, the growth of prostate cancer cells." (PMID 25537508, 2015). "However, we were able to achieve stable, shRNA-mediated FKBP52 knockdown in 22Rv1 prostate cancer cells, which express both full length AR and a constitutively active, truncated AR protein that supports AR-dependent growth in the absence of full length AR activity." (PMID 26207810, 2015). "As PC3 cells are androgen-independent prostate cancer cells, our findings indicate that this improvement of PC3 cell viability probably is not related to AR expression." (PMID 26295055, 2015). "We determined that the levels of ER stress proteins were altered after EBR treatment in LNCaP AR (+), and the same profile was also observed in the non-functional AR-expressing DU145 prostate cancer cell line." (PMID 26353013, 2015). "In prostate cancer, ELK1-shRNA expression resulted in a significant decrease in the growth of androgen-sensitive/AR-positive LNCaP cells cultured with R1881, but not in that of LNCaP cultured without androgens or that of AR-negative cells." (PMID 26342199, 2015). "Unlike in prostate cancer, where AR agonists induce more genes than they repress, in MDA-MB-231-AR tumors, GTx-027 inhibited 2.5X the number of genes (1092 vs. 456) than it activated." (PMID 25072326, 2014). "We thus propose the presence of a negative feedback loop in prostate cancer cells whereby AR activates AMPK and AMPK feeds back to limit AR-driven transcription." (PMID 25003216, 2014). "In prostate cancer cells, CAMK2N1 and AR signaling form an auto-regulatory negative feedback loop, where CAMK2N1 is down regulated by AR activation in response to androgen, while CAMK2N1 inhibits AR expression and activity through the CAMKII and AKT pathway." (PMID 25296973, 2014). "We then went on to show that activation of AMPK decreased AR activity and nuclear localisation, suggesting the presence of a negative feedback loop between AMPK and AR in prostate cancer cells." (PMID 25003216, 2014). "As DU-145 is an AR-independent cell lacking AR protein expression, the predicted path from AR to OCIAD2 in prostate cancer needs more support of more biological experiments." (PMID 24949437, 2014). "As expected, AR was visualized and found to be nuclear in the AR-positive cell line LAPC-4, but absent in the AR-negative prostate cancer cell line DU145." (PMID 25424879, 2014). "Classic NEPC subtype do not express AR and thus do not respond to ADT These “aggressive” prostate cancers rarely arise “de novo”, and most often appear after ADT, at a frequency of 10 to 20%." (PMID 25277175, 2014). "For example, ERG signaling did not exert repressive effect on AR expression of ERG-negative and moderate ERG expressing prostate cancer cells." (PMID 24739220, 2014). "Since the only known target of Casodex is the AR, we interpreted the failure of Casodex to induce a TIF response in AR-negative PC3 prostate cancer cells as due to the absence of AR." (PMID 23363843, 2013). "Having demonstrated a transactivation capacity of FUS that was independent of the promoter in prostate cancer cells we next evaluated the involvement of FUS specifically in AR transcriptional activity at target genes." (PMID 21909421, 2011). "Based on these results, we believe that the down-regulation of AR expression by isoflavone to induce apoptotic cell death could be an important strategy for the prevention and/or treatment of prostate cancer, especially castrate resistant prostate cancer for which there is no curative treatment." (PMID 22200028, 2011). "In order to determine the prostate-specificity of the Ad/GFPDiSTRES vector, two prostate cancer cell lines, LNCaP and PC3/AR, and two non-prostate cell lines, HeLa and U251MG, were chosen for in vitro analysis." (PMID 17295927, 2007).
prostate carcinoma (continued). "Prostate cancer stem cells (PCSC) are rare, undifferentiated cells that do not express the AR and are not dependent on androgens for survival." (PMID 16983403, 2006). "To exclude that the suppression of PSA transcription was specific to LNCaP cells we also examined the effect of pcDNA3-C/EBPα on the PSA promoter/enhancer in two other prostate cancer cell lines, ALVA101 and PC3, neither of which express AR or PSA." (PMID 16774685, 2006). "The only previous report linking CRAT to AR demonstrated that CRAT expression and activity are higher in AR-positive PC3 and LNCaP prostate cancer cells compared to AR-negative PNT2 cells but did not perturb AR to demonstrate a causal relationship between AR and CRAT expression." (PMID 41216931, 2025). "The promoter of TRPM4 that is functional in prostate tissues and prostate cancer did not possess clustered binding sites for ERG, AR, TCF4 or Slug but did have multiple binding sites for SMAD transcription factors, suggesting dominant regulation by the TGFβ pathway." (PMID 40332161, 2025). "Furthermore, there is still no consensus regarding YAP’s dual regulatory effects on AR signaling, which is crucial for developing YAP-targeted therapeutic strategies in prostate cancer." (PMID 39963114, 2025). "However, neither ERG nor AR possess clustered promoter binding sites in the promoter of the MCOLN2 gene and, therefore, MCOLN2 up-regulation in prostate cancers with ERG over-expression is not directly performed by these transcription factors." (PMID 40332161, 2025). "Despite AR not being significantly upregulated in the LM, there may still be some regulation of ALDH1A1 by AR as has been previously demonstrated in prostate cancer." (PMID 38361046, 2024). "In addition, in recent years, many non-targeted AR pathway therapies, such as PARP inhibitor or immune therapy, have been explored and discovered, aiming to explore new ways of prostate cancer treatment and combination drugs to enhance the therapeutic effect." (PMID 39097593, 2024). "Prostate cancer does not show an evident co-occurrence pattern, and almost all edges have a weight of 1, however, there were some central nodes including CTNNB1, RB1, and AR." (PMID 39040139, 2024). "Both in vitro and in vivo experiments utilizing GLP-1R agonist exendin-4 demonstrated decreased proliferation of prostate cancer cell lines by inhibiting the extracellular signaling-regulated kinase/mitogen-activated protein kinase (ERK/MAPK) pathway, independent of the androgen receptor axis." (PMID 39931650, 2024). "AR is recruited to a negative androgen response element on the promoter of SRD5A3 and the different expression levels of 5α-reductase isoenzymes affect patient response to 5α-reductase inhibitors in prostate cancer." (PMID 39680264, 2024). "Interaction between AR and any one of these factors has not been previously reported in the context of breast cancer, but JUNB and ERF have been identified as AR interacting proteins in two LNCaP-derived cell line models of prostate cancer." (PMID 38317241, 2024). "Because PARP7 is expressed in AR-negative metastatic tumors and RBN2397 can affect cancer cells through multiple mechanisms, PARP7 may be an actionable target in advanced prostate cancer." (PMID 37077937, 2023). "Consistent with this, GnRH2 expression is elevated in prostate cancer cells (e.g., LNCaP cells) that produce androgen receptors (ARs) compared to those lacking ARs (e.g., PC3 cells) and AR inhibition blocked androgen-mediated increases in GnRH2 expression in LNCaP cells." (PMID 38260130, 2023).